ZNF511-PRAP1 (ZNF511-PRAP1 readthrough)
Gene: Protein-coding gene on chromosome 10 (133,309,410 to 133,352,529, forward strand). Ensembl gene ENSG00000283496.
Genetic constraint (gnomAD): Loss-of-function variants: 35 observed, 36.37 expected, observed/expected ratio (o/e) 0.96, 90% interval 0.73 to 1.28. The upper end of that interval is the gene's LOEUF score, 1.28, which puts it in group 5 of 6, group 1 being the genes least tolerant of losing a copy. Missense variants: 380 observed, 437.57 expected, observed/expected ratio (o/e) 0.87, 90% interval 0.8 to 0.94. Synonymous variants: 176 observed, 177.39 expected, observed/expected ratio (o/e) 0.99, 90% interval 0.88 to 1.12.